AQP4 (aquaporin 4)
Diseases named in the same sentence as AQP4 in open-access papers (continued):
Sharing a sentence is not in itself a finding about the gene and the disease.
neurodegenerative disease (51 papers, 2016 to 2026). A disorder of the central nervous system characterized by gradual and progressive loss of neural tissue and neurologic function. "Redistribution or decreased expression of AQP4 impairs glymphatic function and is closely associated with neurodegenerative diseases such as AD, PD, and CTE." (PMID 40012567, 2025). "Deficits in the glymphatic system, like lowered expression of AQP4, aging-related disorders, and sleep disruptions, lead to the buildup of harmful proteins like Aβ and increase the risk of neurodegenerative diseases such as AD." (PMID 39077280, 2024). "Aging is known to be a risk factor for the development of PD and other neurodegenerative diseases, and it has been suggested to be one of the most important factors affecting AQP4 localization and expression as well." (PMID 38338949, 2024). "Traumatic brain injury, a risk factor for neurodegenerative diseases, was shown to promote tau pathology in an AQP4-deficient mouse model." (PMID 36768495, 2023). "The study of AQP4 polymorphisms has amplified the knowledge of genetic predisposition to neurodegenerative diseases and underscored the association of AQP4 polymorphisms with cognitive performance in AD and PD in the pathophysiology of these diseases." (PMID 36140362, 2022). "The human AQP4 gene harbors several single nucleotide polymorphisms (SNPs) associated with AQP4 expression, brain-water homeostasis, and neurodegenerative diseases." (PMID 32369477, 2020). "Targeting AQP4 is expected to be new strategies for the treatment of neurodegenerative diseases associated with aggregation of toxic metabolites." (PMID 30867902, 2019). "Decreased expression of pro-inflammatory genes, which are associated with neurodegenerative disease or astrocyte and microglia phenotypes Cd40, C1qB, Cd68, Cd45, Aqp-4, Il1α, Fkbp5, Ggta1, Cd16, H2-T23, and Serping1, was observed following C-32:6 treatment and C1qC, Tspo, and Gbp2 with FFA C-34:6." (PMID 37740008, 2023). "Furthermore, as both NEFM, NPTXR, VGF and AQP4 have been implicated in other neurodegenerative disease in addition to FTD, it cannot be stated here that the profiles of the proteins included in the panel are specific for FTD." (PMID 34838088, 2021). "Individuals with AQP4 variant rs72878776 may be at greater risk for neurodegenerative diseases due to impaired glymphatic function accompanied by poor sleep quality." (PMID 33134185, 2020). "Detecting changes in BBI permeability to water may identify distinct pathological processes at the BBI (e.g. loss of AQP4 polarisation) that may occur at earlier stages of neurodegenerative disease progression prior to the opening of the endothelial layer." (PMID 30557661, 2019). "Alterations in the expression of AQP4 has been linked to neurodegenerative diseases." (PMID 31911786, 2019). "Alterations in AQP4 expression and polarization occur in neurodegenerative diseases, with depolarized AQP4 expression observed to occur in line with disease progression." (PMID 41465272, 2025). "Furthermore, AQP4 pathologies have been found to be associated with the deposition of neurotoxic proteins such as Aβ and α-synuclein (α-syn), suggesting that the development and progression of neurodegenerative diseases should be triggered by the disruption of glymphatic system." (PMID 40012567, 2025). "Aquaporin 4 (AQP4) is the major water transporter in the central nervous system and is implicated in neurodegenerative diseases, such as AD." (PMID 37139088, 2023). "Alterations in any of the components, including AQP4, of this multifactorial pathway, may lead to an impaired glymphatic waste clearance function causing the accumulation of waste and neurotoxic proteins (e.g., Aβ, tau) which contribute to neurodegenerative diseases." (PMID 36614315, 2023). "Our aim was to investigate the relationship between neurodegenerative diseases and two putative glymphatic system biomarkers: AQP4 and EPVS." (PMID 37547746, 2023).
neurodegenerative disease (continued). "The proper localization of AQP4 in end foot processes of astrocytes is essential to its function, and in neurodegenerative diseases with chronic inflammation, increased ROS and glial cell reactivity, AQP4 becomes localized to the cell body." (PMID 33134185, 2020). "Change in the AQP4 distribution from a perivascular to a parenchymal pattern, also known as the depolarization of AQP4, has been reported in various animal and human studies of various neurodegenerative diseases." (PMID 32967251, 2020). "Due to the dynamic role that astrocytes play in neurodegenerative diseases, in this study we analysed how the expression of AQP4 in the white and grey matter changes in the occipital cortex obtained from young and old non-demented humans." (PMID 32059400, 2020). "Astrocytes also express the excitatory amino acid transporters (EAATs) and aquaporin-4 (AQP4) water channel, which are involved in both physiological functions and neurodegenerative diseases (ND)." (PMID 32012713, 2020). "Our findings suggest a novel role for AQP4 in brain neurodegeneration and an opportunity for the development of new therapeutic approaches to treat neurodegenerative diseases." (PMID 30680924, 2019). "Aquaporin-4 (AQP4) deficiency impairs the clearance of interstitial solutes in the ISF, and a decrease in its expression has been demonstrated in neurodegenerative diseases." (PMID 30271658, 2018). "It was discovered that amyloid-β was cleared along the glymphatic pathway, and AQP4-null mice showed a reduction in CSF flux of 65%, and a reduction in amyloid-β clearance of 55%, suggesting a role of AQP4 in neurodegenerative diseases such as Alzheimer’s." (PMID 28036023, 2016). "Recognizing AQP4 as a dynamic regulator of fluid transport, blood–brain barrier functions, and neuroimmune balance, rather than a passive architectural component, will fundamentally change our understanding of neurodegenerative disease." (PMID 41373689, 2025). "Altered AQP4 expression and polarisation are increasingly reported in neurodegenerative diseases, with decreasing AQP4 vessel polarisation hypothesised to contribute to impaired waste clearance and pathogenic protein accumulation." (PMID 39921702, 2025). "Accumulating data have shown that disturbances in AQP4-dependent glymphatic clearance in the brain may play a crucial role in the development of PD and other neurodegenerative diseases." (PMID 38338949, 2024). "Even though the brain’s CSF drainage function is an integrated system involving various compartments, the glymphatic system and AQP4 could serve as intervention targets in neurodegenerative diseases." (PMID 37508938, 2023). "Drugs like this novel AQP4 facilitator might hold a promising future in preventing, treating, or ameliorating neurodegenerative diseases in which the AQP4 functionality is impaired." (PMID 36920936, 2023). "Changes in perivascular localization of AQP4 have beenreported across myriad pathological conditions, including CNS tumours, neurovasculardisorders, such as ischaemic stroke and traumatic brain injury, and in the settingof neurodegenerative disease." (PMID 34499128, 2022). "Even if neurofluid drainage function of the brain is an integrated system based on different compartments, the glymphatic system and AQP4 could be considered intervention targets in neurodegenerative diseases." (PMID 36140362, 2022). "Due to its involvement in CNS water homeostasis, AQP4 has emerged as a potential drug target in neurodegenerative diseases and CNS edema, and it was recently demonstrated that targeting AQP4 subcellular relocalization in astrocytes is a viable strategy for CNS edema following traumatic injury." (PMID 36077012, 2022). "Finally, we investigated how the severity of neurodegenerative disease affects AQP4 expression by comparing white and grey matter of occipital cortex obtained from human cases of moderate or severe CAA." (PMID 32059400, 2020).
neurodegenerative disease (continued). "Because of the various functions of AQP4 in the brain, it might be useful to focus on AQP4 as a therapeutic target for neurodegenerative diseases." (PMID 27517922, 2016). "Thus, we can conclude that the role of AQP4 in the development of PD and other neurodegenerative diseases is a challenging line of research, and many gaps in our knowledge concerning the mechanisms of its involvement remain unfilled and require further human and animal studies." (PMID 38338949, 2024). "Therefore, pharmacological interventions that enhance water exchange through AQP4 and enhance clearance via glymphatic transport might be promising therapeutics for neurodegenerative diseases, by preventing the accumulation of harmful solutes in the brain." (PMID 36920936, 2023). "Therefore, it is possible that they have a mechanism in common which is not shared by other neurodegenerative diseases, despite the strong association between AQP4 and tau protein suggesting otherwise." (PMID 36115967, 2022). "Therefore, considering the critical role of AQP4 in the clearance systems in brain, an understanding of its regulation mechanisms is of critical importance in the therapy field of the protein clearance dysfunction related neurodegenerative disease." (PMID 35991296, 2022). "Besides, AQP4 is thought to play a role in neurodegenerative diseases, including AD, PD, and ALS." (PMID 35991296, 2022). "However, the hypothesis of higher concentrations of AQP4 in CSF of people suffering from neurodegenerative disease seems more conceivable." (PMID 36115967, 2022). "Finally, the author would like to hypothesize on AQP4’s role in interaction between reactive astrocytes and reactive microglial cells, which might occur in neurodegenerative diseases." (PMID 27517922, 2016). "Furthermore, a therapeutic strategy for AQP4-related neurodegenerative diseases is proposed." (PMID 27517922, 2016). "Recent studies have demonstrated that the specific water channel protein, aquaporin-4 (AQP4), plays a role in the pathogenesis of neurodegenerative diseases involving protein clearance system." (PMID 35991296, 2022). "Recent findings regarding APOE4 and AQP4 haplotypes, as well as the effect of sleep on PVS, demonstrate the complex nature of this neurodegenerative disease." (PMID 36330347, 2022). "Conversely, the increased brain iron in aging and neurodegenerative diseases was correlated with decreased BBB water exchange rate as the kw index, which could be the result of dysfunctions of the perivascular AQP4 channels." (PMID 37592310, 2023). "In a recent study, significantly higher levels of AQP4 were found in AD and FTD patients compared to subjects not affected by neurodegenerative diseases, and a significant, positive correlation between AQP4 and total Tau levels was found." (PMID 36140362, 2022). "Significantly higher levels of AQP4 were found in AD and FTD patients compared to subjects not affected by neurodegenerative diseases, and a significant, positive correlation between AQP4 and total tau levels was found." (PMID 36115967, 2022).
infection (33 papers, 2007 to 2026). The state of being infected such as from the introduction of a foreign agent such as serum, vaccine, antigenic substance or organism. "AQP4 mislocalization is also closely associated with astrocytic reactivity, a process that naturally occurs with aging or in response to stressors such as injury, neurodegeneration, or infection." (PMID 40746364, 2025). "Significant changes were also found in the hippocampus region for AQP4 water channel protein due to both infection and genotype, the association between AQP4 expression and Iba1+ perimeter was further explored for both non-infected and infected groups in this brain region." (PMID 40051735, 2025). "Notably, our previous report demonstrated that S. apiospermum infection caused decreased expression of AQP-4 in the brain of immunosuppressive mice, proving that severe diseases, such as cerebral edema is associated with this infection." (PMID 33563219, 2021). "A possible hypothesis linking infection with the Epstein–Barr virus, a well identified causal step in MS, and the development of the disease is that mechanisms such as poor sleep or less functional AQP4 polymorphisms may sustain glymphatic flow reduction." (PMID 40722356, 2025). "A more probable hypothesis is that any infection that derives in immune system imbalance, causing over-reactivity, production of self-reactive lymphocytes and AQP4, enhanced levels of cytokines and damage to the blood–brain barrier may be involved in the onset or exacerbation of NMOSD." (PMID 37374092, 2023). "Although the suppression of the complement pathway and neutrophils is suitable for relapse prevention of AQP4+ NMOSD, there is a high risk of infection in such conditions." (PMID 41596603, 2026). "Following the observation of increased BBB water-exchange in infected rats, we sought to determine the impact of infection on the AQP4 protein, a water-channel protein located on astrocyte endfeet and closely interfaced with the microvasculature." (PMID 40051735, 2025). "When animals were reinfected at 18-months, the hippocampus ANOVA showed significant upregulation in AQP4 due to infection (+25%, P = 0.02) and significantly lower AQP4 in the TgF344 rats than in their WT counterparts (−21%, P = 0.01)." (PMID 40051735, 2025). "Our results suggest that there is an upregulation of AQP4 proteins during infection, which correlated with BBB water exchange measurements, particularly in the hippocampus region, which is affected early in the pathogenesis of Alzheimer’s disease." (PMID 40051735, 2025). "An ex vivo study exposing primary human cortical tissue slices to SARS-CoV-2 showed that 90% of infected cells expressed GFAP and aquaporin 4, suggesting a dominant infection of astrocytes in comparison to neurons and other glial cells." (PMID 37516868, 2023). "We find that an increase in BBB water permeability during infection is associated with higher levels of plasma von Willebrand factor, a marker of vascular inflammation, and that infection leads to higher levels of astrocytic AQP4 which may drive the observed increases in BBB water exchange." (PMID 37013549, 2023). "In experimental mice model, Herpes simplex virus (HSV) decreased AQP4 in the acute phase of infection but increased its expression along with AQP1 in the long-term infection." (PMID 33796134, 2021). "We further compared the absolute number of Th2 cells in spleens, mesenteric lymph nodes and livers of AQP4 KO and WT mice after infection." (PMID 25604731, 2015). "Since week 5 post-infection, the proportion of Th2 cells in both AQP4 KO and WT mice increased markedly with a more rapid increase in the proportion of Th2 cells observed in AQP4 KO group." (PMID 25604731, 2015). "No later than 5 weeks post-infection, the average size of liver granuloma showed a quicker exacerbation in AQP4 KO mice and it was significantly larger than that in the WT mice 8 weeks post-infection." (PMID 25604731, 2015).
infection (continued). "During infection, the type of cell death (apoptosis or necrosis) of AQP4-expressing cells is important for priming AQP4-specific-T cells." (PMID 18510734, 2008). "With the new criteria for NMO it would be very useful to track such infection related cases with respect to anti-AQP4-specific antibody at the time of presentation after recovery or at autopsy." (PMID 18510734, 2008). "All had recovered from the infection by the time they were hospitalized for MOG-ON/AQP4-ON." (PMID 38988608, 2024). "Therefore, our results suggest that severe cerebral edema induced by TMMI-012 infection is at least partially due to the poor AQP-4 response." (PMID 33563219, 2021). "Thus, our present findings demonstrate that the reduction of AQP-4 expression affects the severity of cerebral damage during TMMI-012 infection." (PMID 33563219, 2021). "Our study revealed that the infection disease pathway might be involved in the pathogenesis of AQP4-positive NMOSD." (PMID 34367251, 2021). "However, pathogenic AQP4-specific antibodies could also form as consequence of paraneoplastic events, or in sequel to infections (e.g. tuberculosis, different herpes virus infections, Dengue virus infections, hepatitis, or events summarized as “common cold” and “feverish infection”." (PMID 32293546, 2020). "However, at each time point post-infection, the proportion and the absolute number of Treg cells in AQP4 KO mice were significantly less." (PMID 25604731, 2015). "Consistently, more Th2 cells were present in AQP4 KO mice after 5 weeks post-infection." (PMID 25604731, 2015). "However, at 3 weeks post-infection, the level of IgG2a in AQP4 KO mice was significantly lower than that in WT mice, while at 5 weeks post-infection, a markedly higher level of IgG1 was observed in AQP4 KO mice compared with that in WT mice." (PMID 25604731, 2015). "In addition, the mean fluorescence intensity of IFN-γ expression was lower in Th1 cells from AQP4 KO mice 3 weeks post-infection." (PMID 25604731, 2015). "In addition to the immunofluorescent staining, the transcriptional analysis of parietal cell markers shows that ATP4A and AQP4 were significantly down regulated following a trickle infection, whereas KCNQ1 transcript levels were unchanged in all animals." (PMID 24330735, 2013). "Thus, the increase in AQP4, combined with increased LCN2 expression, might be an underlying event associated with the BBB dysfunction in our mouse model of infection." (PMID 37496672, 2023). "And before the morbidity of NMOSD, there are often incentives such as infection, which may temporarily increase the permeability of the blood–brain barrier in the optic nerve or spinal cord, thus promoting the circulation of AQP4 antibodies into the central nervous system." (PMID 34520629, 2021). "Aquaporin-4 water channels and microglia are found as key BBB components in responding to peripheral infection, however their role (protective or deleterious) is yet to be determined." (PMID 40051735, 2025). "In Ontario, Canada, a study found that population-wide infection control measures to halt SARS-CoV-2 spread in March 2020 significantly reduced MOGAD cases among children, while MS and AQP4-NMOSD rates remained unchanged." (PMID 38988608, 2024). "This is similar to AQP4-IgG-positive NMOSD, which has been reported to be preceded by infection in 20-30 % of cases." (PMID 27793206, 2016). "Similar to AQP4-IgG-positive NMOSD and to MS, disease onset or relapse was preceded by infection or vaccination in several cases." (PMID 27793206, 2016). "After infection with wild type P. aeruginosa and lasI-/rhlI- mutant for 1 h, mRNA levels were slightly affected for AQP0, 1, 2, 3, 8, 11, and 12, with exception for AQP4, 5, 6, 7, 9, and 10 that maintained near to the basal expression level." (PMID 26388857, 2015).